FAM168B (family with sequence similarity 168 member B)
Description:
Inhibitor of neuronal axonal outgrowth. Acts as a negative regulator of CDC42 and STAT3 and a positive regulator of STMN2. Positive regulator of CDC27.
Synonyms: Mani; KIAA0280L
Tractability: Antibody: UniProt places it where antibodies can reach, with medium confidence; UniProt predicts a signal peptide or a membrane-spanning region; its Gene Ontology location is reachable by antibodies, with medium confidence.
Gene: Protein-coding gene on chromosome 2 (131,047,876 to 131,093,487, reverse strand). Ensembl gene ENSG00000152102.
Subcellular location: Cytoplasm, perinuclear region; Cell membrane; Cell projection, axon
Gene Ontology:
Cellular component: extracellular exosome; plasma membrane; axon; membrane; perinuclear region of cytoplasm
Genetic constraint (gnomAD): Loss-of-function variants: 17 observed, 18.54 expected, observed/expected ratio (o/e) 0.92, 90% interval 0.63 to 1.38. The synonymous counts are far from expectation, so gnomAD's model fits this gene poorly and the ratio says little. Missense variants: 214 observed, 222.87 expected, observed/expected ratio (o/e) 0.96, 90% interval 0.86 to 1.08. Synonymous variants: 119 observed, 92.69 expected, observed/expected ratio (o/e) 1.28, 90% interval 1.11 to 1.5.
Homologues: Orthologues: chimpanzee FAM168B (100% identical), macaque FAM168B (100% identical), pig FAM168B (100% identical), dog FAM168B (99% identical), guinea pig FAM168B (99% identical), rabbit FAM168B (98% identical), rat Fam168b (98% identical), mouse Fam168b (98% identical), tropical clawed frog fam168b (91% identical), zebrafish fam168b (86% identical). Paralogues in human: FAM168A (67% identical).
Diseases named in the same sentence as FAM168B in open-access papers:
FAM168B is named in the same sentence as 3 diseases in open-access papers, as found by Europe PMC text mining. Sharing a sentence is not in itself a finding about the gene and the disease. The quoted sentences say what the papers report.
Salmonella Infections (1 paper, 2023). Infections with bacteria of the genus SALMONELLA. "Among the multiple genes detected in this study, EXFABP, S100A9/12, CEMIP, FKBP5, MAVS, FAM168B, HESX1, EMC6, and others were found as potential candidate gene and transcript (co-) factors for resistance to Salmonella infection." (PMID 36902251, 2023).
infection (1 paper, 2023). The state of being infected such as from the introduction of a foreign agent such as serum, vaccine, antigenic substance or organism. "The FAM168B, RAF1, HESX1, USP8, C2CD5, PIGC, ENSGALG00000053041, and ENSGALT00000092369 were found to be top driver genes shared among dpi, body weight post-infection, and propionate and valerate cecal contents." (PMID 36902251, 2023).
FAM168B also shares sentences with these, for which no sentence is quoted: renal carcinoma (1 paper).